ENSG00000275254
Gene: Miscellaneous RNA gene on chromosome X (74,280,936 to 74,281,082, forward strand). Ensembl gene ENSG00000275254.
Gene Ontology:
Biological process: positive regulation of gene expression